IL13 (interleukin 13)
Diseases named in the same sentence as IL13 in open-access papers (continued):
Sharing a sentence is not in itself a finding about the gene and the disease.
airway hyperresponsiveness (continued). "ILC2s are able to rapidly produce large amounts of type 2 cytokines and growth factors, such as IL-5, IL-13, and AREG to initiate type 2 immune responses, induce eosinophilic lung inflammation, airway hyperresponsiveness, mucus hypersecretion, and to drive healing and fibrotic repair." (PMID 39405112, 2024). "We have shown that rhinovirus A1B (RV1B) infection of 6-day-old mice, but not mature mice, induces mucous metaplasia and airway hyperresponsiveness that is associated with ILC2 expansion and dependent on IL-13, IL-25, IL-33, and TSLP." (PMID 38061015, 2024). "However, RSV line 19 infection induced the production of IL-13 and airway mucus, reduced the production of IFN-γ, and produced exaggerated airway hyperresponsiveness." (PMID 36077310, 2022). "The RSV A2 and Long strains produced similar immune responses in mice: predominant IFN-γ production, no production of IL-13 or airway mucus, and no airway hyperresponsiveness." (PMID 36077310, 2022). "Experimental study showed that ablation of T cell–derived IL-10 increased the IFN-γ response to HDM, reducing IL-13 levels and airway eosinophilia without affecting IgE levels or airway hyperresponsiveness." (PMID 34930201, 2021). "We observed a significant reduction of airway hyperresponsiveness (AHR), lung eosinophil and lymphocyte counts, serum IgE, Th2 cytokines (IL-4 and IL-13), goblet cell hyperplasia and mucus production in mice that had reduced GRK2 expression specifically in T cells." (PMID 35386975, 2021). "Neutralization of IL-13 or IFN-γ during Ag plus IL-18 challenges inhibited the combination of eosinophilic infiltration, lung fibrosis, and periostin deposition or the combination of neutrophilic infiltration and airway hyperresponsiveness, respectively." (PMID 34367377, 2021). "Ablation of T cell–derived IL-10 increased the IFN-γ and IL-17A response to HDM, reducing IL-13 levels and airway eosinophilia without affecting IgE levels or airway hyperresponsiveness." (PMID 31445933, 2020). "STAT6 knockout mice did not respond to lL-4 and IL-13, failed to produce IgE, and developed airway hyperresponsiveness after allergen exposure." (PMID 32256362, 2020). "Overall, this study demonstrates that IL-13 stimulation induces production of mucus and biomarkers of allergic inflammation in human lung tissue ex-vivo but no airway hyperresponsiveness." (PMID 30500834, 2018). "Contrary to this, IL-13 did not induce airway hyperresponsiveness (AHR) in human and NHP PCLS, although it was effective in rodent PCLS." (PMID 30500834, 2018). "Airway hyperresponsiveness was augmented at a high ventilation rate (120 per minute) in a murine model of ACO, however, lower eosinophil count and the concentration of IL‐5 and IL‐13 in BALF were observed." (PMID 29368450, 2018). "A delayed and prolonged type 2 immune response which is featured with increased expression of IL-4, IL-5 and IL-13, as well as mucous metaplasia and airways hyperresponsiveness occurs in HRV-infected immature but not in adult mice." (PMID 30513770, 2018). "Murine studies have shown that ILC2s are an early innate source of IL-5 and IL-13 after allergen exposure, which induce airway eosinophilic infiltration, mucus hyperproduction, and airway hyperresponsiveness but not allergen-specific IgE production." (PMID 26965110, 2016). "Specifically, BLT1-null mice with OVA-induced bronchial asthma did not develop airway hyperresponsiveness or eosinophilic inflammation, and had reduced IgE production and decreased IL-5 and IL-13 in BAL fluid, suggesting an attenuated Th2-type response." (PMID 27669173, 2016). "In addition, IL-18 has been observed to be able to induce release of IFN-γ, IL-13, and eotaxin in the lungs of ovalbumin-sensitized and challenged transgenic mice along with an increase in IL-13 producing CD4+ T cells and airway hyperresponsiveness." (PMID 27069315, 2016).
airway hyperresponsiveness (continued). "Therefore, through modulation of these TH2 cytokines, such as IL-5, IL-6, and IL-13, KWLL treatment was able to reduce eosinophils infiltration and airway hyperresponsiveness." (PMID 23533467, 2013). "The treatment of 18β-GA reduced IL-5, IL-13, TNF-α, OVA-specific IgE level and total IgE level while increased IFN-γ level, thereby helping to reduce the influx of leukocytes, goblet cell metaplasia, and airway hyperresponsiveness, as shown by lung histopathological analysis." (PMID 35210449, 2022). "Evidence to support this hypothesis is demonstrated in double knock-out IL-4/IL-13 mice epicutaneously sensitized with OVA that resulted in increased systemic TH17 responses that affected the lungs after antigen challenge, and resulted in airway inflammation and airway hyperresponsiveness." (PMID 23283176, 2011). "CD86 siRNA treatment ameliorated OVA-induced airway eosinophilia, airway hyperresponsiveness, and the elevations of OVA-specific IgE in the sera and IL-5, IL-13, and CCL17 in the bronchoalveolar lavage fluid, but not the goblet cell hyperplasia." (PMID 25344652, 2014). "LPS-reduced HDE challenge induced significantly higher concentrations of IFNγ, and IL-5 and IL-13 in the BAL fluid, but did not decrease airways hyperresponsiveness or airway resistance to methacholine challenge." (PMID 21345191, 2011).
pulmonary fibrosis (183 papers, 2005 to 2025). Chronic progressive interstitial lung disorder characterized by the replacement of the lung tissue by connective tissue, leading to progressive dyspnea, respiratory failure, or right heart failure. "In bleomycin induced pulmonary fibrosis mice model, TGFβ and IL-13 transgenic pulmonary fibrosis mice models, null mutation or small-molecule inhibition of CRTH2 can prevent the development of pulmonary fibrosis." (PMID 39972424, 2025). "Other important mediators associated with lung fibrosis are legumain, osteopontin, IL-4, IL-6, IL-13, IL-17, TNF-α, Gal-1, Gal-3, PDGF, and FGFR-1." (PMID 38540252, 2024). "Of note, serum IL-31 levels positively correlated with the severity of skin and lung fibrosis and serum levels of IL-4, IL-6, and IL-13, which suggests the association of IL-31 with fibrosis and Th2 immune responses in SSc." (PMID 34642338, 2021). "In mouse models, IL-13 deficiency or defective IL-13 signalling reduced lung fibrosis, whereas overexpression of IL-13 increased lung fibrosis." (PMID 33008934, 2021). "Pulmonary fibrosis caused an increase in the level of IL-13 in the lung homogenate of group 2 mice compared to group 1 mice (d21)." (PMID 33171668, 2020). "Elias and colleagues published that overproduction of constitutive IL-13 in the lungs of adult mice induced pulmonary fibrosis, and overproduction of conditional lung-specific IL-13 leads to emphysema in IL-13 gene deficiency mice." (PMID 32280354, 2020). "IL-13 has been implicated in UC and in other fibrotic diseases including idiopathic pulmonary fibrosis and liver fibrosis but the knowledge of the role of IL-13 in fibrosis in CD is limited." (PMID 31296924, 2019). "IL-13-driven fibrosis is observed in cases of parasitic egg deposition, fungus and virus-associated pulmonary fibrosis, post-irradiation-induced fibrosis, and silicosis." (PMID 29872441, 2018). "Previous studies showed that bleomycin–induced lung fibrosis was diminished in mice deficient in IL-13, IL-4 and their downstream transcription factor STAT6 or treated with a neutralizing anti–IL-13 antibody." (PMID 29782549, 2018). "Our observation that IL-13 deficient mice are exceptionally resistant to radiation-induced pulmonary fibrosis provides a strong rationale for therapeutic strategies targeting IL-13 to mitigate radiation lung injury." (PMID 28004808, 2016). "We and others have shown that IL-13-induced lung fibrosis is associated with activation of AKT and YY1 signaling." (PMID 25775215, 2015). "The Th2 cytokine IL-13 has been shown to promote fibrosis in a number of experimental models, and IL-13-deficient mice exhibit exacerbated lung fibrosis." (PMID 24641440, 2014). "Inducible NOS also contributes to the development of pulmonary fibrosis and underlies the response to a number of pro-fibrotic cytokines, including IL-5 and IL-13." (PMID 24641440, 2014). "Amongst them, IL‐1β, IL‐10, and IL‐13 are associated with pulmonary fibrosis." (PMID 38952051, 2024). "However, a recent study using BALB/c mice has implicated IL-13-dependent accumulation of fibrocytes during OSM-induced lung fibrosis." (PMID 32736577, 2020). "To determine whether IL-13 is a critical factor promoting radiation-induced pulmonary fibrosis we compared the survival duration of wild type and IL-13 deficient mice (IL-13−/−, c57BL/6NTac-[KO]IL13) exposed to thoracic irradiation (n = 15 per group)." (PMID 28004808, 2016). "We evaluated the progression of radiation-induced pulmonary fibrosis in wild-type and IL-13-deficient mice, and characterized the inflammatory milieu in irradiated lung tissue, demonstrating that this cytokine is essential to the development of pulmonary fibrosis." (PMID 28004808, 2016). "The profibrotic effect of IL-13 has been demonstrated in pulmonary fibrosis animal models, in which its overexpression is sufficient to cause fibrosis, whereas its knockout or blockade attenuates pulmonary fibrosis." (PMID 41465549, 2025).
pulmonary fibrosis (continued). "This can occur in various organs, including the lungs, where IL-13 contributes to conditions such as idiopathic pulmonary fibrosis." (PMID 40771803, 2025). "This specific aspect of IL-13’s actions has been discussed in diseases such as systemic fibrosis, idiopathic pulmonary fibrosis, and others." (PMID 40003307, 2025). "IL-13 with IL-33 synergistically stimulates the polarization of M2 macrophages that play an important role during the late pulmonary fibrosis phase." (PMID 40191199, 2025). "Fibroblasts in the lungs are activated and differentiate into myofibroblasts under the influence of cytokines like IL-13 and tumor growth factor-β (TGF-β), with the resulting immune response causing lung fibrosis." (PMID 39458029, 2024). "As pulmonary fibrosis advances, M1 macrophages transition into M2 macrophages, secreting IL-10, IL-13, TGF-β, among others, to mediate the anti-inflammatory and immunosuppressive phases." (PMID 39450276, 2024). "Thereby, supplementary studies are required in order to understand the role of IL-13 in pulmonary fibrosis induced by COVID-19 infection." (PMID 38540252, 2024). "Sim, an inhibitor of 3-hydroxy-3-methylglutaryl coenzyme A used to treat atherosclerotic diseases, has protective effects on bleomycin-induced pulmonary fibrosis in rats by reducing the levels of IL-13 and TGF-β1." (PMID 38720270, 2024). "Previous studies have confirmed that Th2 cytokines play a leading role in pulmonary fibrosis, and its pathogenesis is related to the secretion of IL-4, IL-5 and IL-13." (PMID 39346776, 2024). "Neutralizing IL-13 attenuates both bleomycin-induced pulmonary fibrosis and Ccl6 levels, suggesting a role for Ccl6 in the development of fibrosis." (PMID 39768150, 2024). "Elevated levels of Ccl6 are observed during the pathogenesis of bleomycin-induced pulmonary fibrosis, and its expression is induced by the Th2 cytokine IL-13." (PMID 39768150, 2024). "IL-13 promoted pulmonary fibrosis in radiation-induced lung fibrosis models, whereas IL-13 inhibition decreased fibrotic changes in the IPF model in vivo." (PMID 39596365, 2024). "For example, IL‐13 blockade has been shown to be beneficial in patients with idiopathic pulmonary fibrosis and COPD." (PMID 39606183, 2024). "We also observed a significant increase in IL-4 and IL-13 levels in plasma in ES silicotic patients, both cytokines are mainly associated with the TH2 response and associated with inflammation and lung fibrosis." (PMID 36675056, 2023). "In this regard, the activation of β-catenin in alveolar cells promotes pulmonary fibrosis, in a process that reminds IL-13-mediated fibrosis." (PMID 37963919, 2023). "Type 2 cytokines, such as TGF-β1, interleukin-13 (IL-13) and IL-5, are essential for the development of lung fibrosis by promoting production of extracellular matrix proteins and inducing myofibroblast differentiation." (PMID 37457733, 2023). "Several studies indicate that type 2 cytokines (IL-4 and IL-13) are profibrotic and stimulate type 1 collagen production by fibroblasts in pulmonary fibrosis." (PMID 36976645, 2023). "IL-13 is another Th-2 cytokine that has been shown to play a key role in lung fibrosis and increased expression of IL-13 was repeatedly reported in IPF." (PMID 37063828, 2023). "IL-13, also known as a Th2 cell cytokine, ameliorates lung fibrosis in the experimental mouse model." (PMID 35268581, 2022). "IL-13 and its receptors are elevated in IPF bronchoalveolar lavage fluid, while neutralization of IL-13 attenuated bleomycin-induced pulmonary fibrosis." (PMID 35672815, 2022). "The implementation of antibody-based therapy against IL-13 (Anti-IL-13) in treating PF revealed that a potent candidate, tralokinumab, reduced matrix accumulation, lung apoptosis, and lung fibrosis." (PMID 35268581, 2022). "IL-13 contributes to the process of lung fibrosis in human TB, since MCs are abundant in fibrotic sites of human pulmonary TB-associated lesions." (PMID 35886897, 2022).
pulmonary fibrosis (continued). "TH2 cytokines, in particular IL-4 and IL-13, have also a role in the differentiation of M2 macrophages, that in turn have a role in the development of pulmonary fibrosis through the secretion of TGF-β." (PMID 35386702, 2022). "IL-13 and CCL2 secreted by Th2 were implicated in the pathogenesis of lung fibrosis models, including in idiopathic pulmonary fibrosis." (PMID 36148463, 2022). "Th2 cytokines, such as transforming growth factor (TGF)-β, interleukin (IL)-4, and IL-13, enhance the development of pulmonary fibrosis by activating fibroblast proliferation and collagen production." (PMID 35606782, 2022). "Animal models provide evidence that IL-33 is able to induce both cutaneous and pulmonary fibrosis via increased IL-13 and in SSc patients the levels of IL-33 correlate with skin fibrosis." (PMID 35252259, 2022). "The Jak−STAT pathway is activated by several cytokines, such as IL-6, IL-4, IL-13, and TGF-β, which are implicated in the pathogenicity of pulmonary fibrosis." (PMID 36556326, 2022). "TGF-β and IL-13 can induce myofibroblast differentiation and stimulate the production of extracellular matrix components, which contribute to pulmonary fibrosis." (PMID 35634336, 2022). "Basic research confirmed that IL-13 is an important cytokine for epithelial mesenchymal transition (EMT) to promote pulmonary fibrosis." (PMID 35592688, 2022). "For instance, the IL-33/Akt1 pathway regulates pulmonary fibrosis by enhancing the production of the profibrotic cytokine IL-13 by macrophages." (PMID 36362440, 2022). "Our previous work has depicted the effector mechanism of IL-4/IL-13 signaling in the pathogenesis of pulmonary fibrosis and the upregulation of IL-31RA via the IL-4Rα/STAT6 signaling axis." (PMID 33815402, 2021). "Congruently, overexpression of GATA3, a transcription factor implicated in TH2 differentiation leads to augmented lung collagen deposition while animals in which IL-4 and IL-13 has been modulated, are protected from bleomycin-induced lung fibrosis." (PMID 34093523, 2021). "Both IL-4 and IL-13 are main type 2 cytokines produced by T helper 2 cells that play a critical role in pulmonary fibrosis." (PMID 34461906, 2021). "T-helper (Th) 1 secretes IFN-γ to reduce pulmonary fibrosis, whereas Th2 cytokines IL-4, IL-5, and IL-13 stimulate fibroblast proliferation, collagen production, and fibroblast activation." (PMID 33647885, 2021). "IL-4 and IL-13 are related to ILDs and are required for the maintenance of pulmonary fibrosis, modulating the abnormal activation of lung fibroblast." (PMID 34207510, 2021). "A subsequent manuscript describing roles for HIMF (FIZZ1) found that pulmonary fibrosis was a result of HIMF-regulated Th2-mediated mechanisms likely via IL-4 an IL-13 since HIMF expression was significantly decreased in IL-4 and IL-13 knockout mice." (PMID 33800244, 2021). "In AECs from both a BLM-induced fibrosis mouse model and pulmonary fibrosis patients, IL-4 and IL-13 mediate their fibrotic effect by binding to the receptor and activating JAK1." (PMID 34207510, 2021). "CD103high Tregs can constrain lung fibrosis induced by CD103low tissue-resident pathogenic CD4+ T cells with higher production of effector cytokines, such as IL-4, IL-5, IL-13, IL-17A, and IFN-γ." (PMID 34488453, 2021). "Previous studies have identified important roles for Th2 T cell-derived IL-4 and/or IL-13 in the development of pulmonary fibrosis and other fibrotic diseases." (PMID 33815402, 2021). "This phase 2, randomised, double-blind, placebo-controlled trial evaluated the efficacy and safety of lebrikizumab, an interleukin (IL)-13 monoclonal antibody, alone or with background pirfenidone therapy, in patients with idiopathic pulmonary fibrosis (IPF)." (PMID 33008934, 2021). "BRP39/YKL40 also participates in the immune inflammatory response of pulmonary fibrosis, promotes Th2 cell immunity, regulates the release of IL-13, and activates macrophages." (PMID 33101446, 2020).